HOXB-AS1 (HOXB cluster antisense RNA 1)
Synonyms: HOXB3OS
Gene: Long non-coding RNA gene on chromosome 17 (48,543,002 to 48,554,788, forward strand). Ensembl gene ENSG00000230148.
Diseases named in the same sentence as HOXB-AS1 in open-access papers:
HOXB-AS1 is named in the same sentence as 8 diseases in open-access papers, as found by Europe PMC text mining. Sharing a sentence is not in itself a finding about the gene and the disease. The quoted sentences say what the papers report.
glioblastoma (3 papers, 2021 to 2022). The most malignant astrocytic tumor (WHO grade IV). "For example, HOXB-AS1 has been evaluated for its upregulated levels in glioblastoma cells and is directly associated with patient’s survival." (PMID 36045719, 2022). "The proliferation, migration, and invasion of glioblastoma cells are regulated by HOXB-AS1, which modulates the miR-885-3p/HOXB2 axis." (PMID 39280958, 2022). "HOXB cluster antisense RNA 1 (HOXB-AS1) has been demonstrated to facilitate the proliferation of glioblastoma cells, endometrial carcinoma, and multiple myeloma cells." (PMID 34888348, 2021). "Studies have shown that inhibition of miR-885-3p expression can antagonize HOXB-AS1 knockdown and further affect the expression of HOXB2 in human glioblastoma tissues and cells." (PMID 39280958, 2022).
glioma (3 papers, 2021 to 2025). A benign or malignant brain and spinal cord tumor that arises from glial cells (astrocytes, oligodendrocytes, ependymal cells). "For instance, HOXB-AS1 has been shown to have significantly higher expression levels in glioma compared to low-grade glioma tissues." (PMID 39980564, 2025). "To further investigate the biological role of HOXB-AS1 in glioma cells, we depleted the expression of HOXB-AS1 using lncRNA Smart Silencer." (PMID 34805277, 2021). "Furthermore, HOXB-AS1 plays a key role in several cancers, including glioma and colon cancer, and is presumed to play an oncogenic role in gastric cancer." (PMID 39280958, 2022).
endometrial carcinoma (2 papers, 2021). A malignant tumor arising from the epithelium that lines the cavity of the uterine body. "For instance, HOXB-AS1, which might function as a carcinogen and a promising therapeutic biomarker for the clinical treatment of patients with multiple myeloma, GBM, and endometrial carcinoma patients, has been shown to regulate cancer cell proliferation, migration, and invasion." (PMID 34805277, 2021).
gastric cancer (1 paper, 2022). A primary or metastatic malignant neoplasm involving the stomach. "We found that Na2SeO3 inhibited the expression of HOXB-AS1 in gastric cancer cells and regulated the expression of related proteins to inhibit cell proliferation and migration and promote apoptosis after the overexpression of HOXB-AS1 in HGC-27 cells." (PMID 39280958, 2022).
cancer (5 papers, 2021 to 2025). A tumor composed of atypical neoplastic, often pleomorphic cells that invade other tissues. "The HOXB cluster antisense RNA 1 (HOXB-AS1) is related to cancer cell proliferation, migration, and invasiveness, which could become a biomarker for early diagnosis and prognosis." (PMID 41440381, 2025). "A recent study has shown that HOXB-AS1 plays a part in pathways related to cancer and the immune system, indicating its potential involvement in the development of cancer and immune regulation in various types of cancer." (PMID 38284893, 2024). "Long non-coding HOXB cluster antisense RNA 1 (HOXB-AS1) is a tumor exciter in various cancers." (PMID 36045719, 2022). "Furthermore, sphere formation assay revealed that HOXB-AS1 knockdown inhibited spheroid formation in GSCs, indicating that HOXB-AS1 supports cancer stem cell growth." (PMID 34805277, 2021).
HOXB-AS1 also shares sentences with these, for which no sentence is quoted: multiple myeloma (2 papers); colon cancer (1); tumor (1).